EGFR (epidermal growth factor receptor)
Diseases named in the same sentence as EGFR in open-access papers (continued):
Sharing a sentence is not in itself a finding about the gene and the disease.
colitis (continued). "Both, Cldn2KO mice and WT mice receiving EGFR inhibitor showed impaired recovery from colitis." (PMID 37815870, 2023). "Furthermore, in WT mice recovering from colitis, inhibiting EGFR signaling inhibited CLDN2 upregulation and MH." (PMID 37815870, 2023). "Inhibiting EGFR activation impaired recovery from colitis and resulted in mouse death." (PMID 37815870, 2023). "EGFR activation contributes to multiple protective cellular effects in colitis." (PMID 36159834, 2022). "In this study, we identified a glucose-free, high-protein diet (GFHPD) to prevent high glycolysis activity while boosting amino acid metabolism, thereby reducing CRC burden with similar efficacy as EGFR-directed antibody therapy in an experimental mouse model of colitis-driven CRC." (PMID 34830971, 2021). "For example, comparing the protein expression profile of colorectal exosomes isolated from healthy mice and DSS-induced colitis model mice, model mice-derived exosomes significantly promoted cell proliferation in an epidermal growth factor receptor (EGFR)-dependent manner." (PMID 34683937, 2021). "Similarly, MyD88-dependent signaling by radioresistant, non-myeloid cells has been shown to provide protection from inflammation in a chemically induced model of colitis via enhanced signaling through the epidermal growth factor receptor (EGFR)." (PMID 25346729, 2014). "Moreover, the EGFR pathway is involved in the maintenance of gut barrier integrity in mammals and is important in preventing the development of colitis." (PMID 21176204, 2010). "Hence, we examined if colitis-induced CLDN2 upregulation depends on EGFR activation." (PMID 37815870, 2023). "EGFR has been reported to participate in many biological functional processes, such as the proliferation, differentiation, and survival of cells; meanwhile, activating EGFR can help to alleviate inflammation and further limit the progression of colitis lesions." (PMID 36362252, 2022). "Similarly, the ADAM17ex/ex mouse displayed increased susceptibility to dextran sulfate induced colitis, due to a lack of EGFR signaling and STAT3 activation." (PMID 33579029, 2021). "Furthermore, mice with markedly reduced TACE activity show increased susceptibility to acute colitis, probably due to a lack of EGFR signaling." (PMID 29491382, 2018). "While the precise mechanisms governing ADAM17- and EGFR-mediated protection against DSS-induced colitis remain unknown, the ErbB ligands and known ADAM17 substrates amphiregulin (AREG), epiregulin (EREG), and transforming growth factor (TGF)-α appear to be key effectors." (PMID 29312533, 2017). "Enhanced EGFR expression induced by TNF-α promotes GPCR-mediated EGFR transactivation in colonic myofibroblasts, providing an important mechanism for stromal COX-2 over-expression that may predispose to the development of colitis-associated cancer." (PMID 23688423, 2013). "Gefitinib, a first‐generation EGFR‐TKI, has been shown to exacerbate colitis in a mouse model of induced colitis." (PMID 40641492, 2025). "To examine this in vivo, we inhibited EGFR signaling (gefitinib; 200 mg/kg body weight; oral gavage) in WT mice recovering from DSS-induced colitis." (PMID 37815870, 2023). "Here, we have examined these issues using an animal model of colitis and CAC that allows testing the effects of EGFR modulation at different timepoints emulating active flares, healing, and remission in IBD patients." (PMID 29904166, 2018). "Recently, a study suggested that the activation of EGFR by its ligand, amphiregulin (AREG), enhances the function of Tregs in a colitis and tumour vaccination model." (PMID 28541302, 2017). "Further, the soluble proteins from Lactobacillus GG (LGG) in fermented milk activated epidermal growth factor receptor (EGFR) and anti-apoptotic factor (Akt) in young adult mouse colon cells, and this activation is attributed to the reduction in colitis." (PMID 26347738, 2015).
colitis (continued). "Here, we demonstrate, for the first time, that enhanced EGFR expression induced by TNF-α facilitates GPCR-mediated EGFR transactivation in colonic myofibroblasts, providing an important mechanism for stromal COX-2 over-expression that may predispose to the development of colitis-associated cancer." (PMID 23688423, 2013). "Deletion of EGFR in macrophages in DSS-colitis mice leads to the increase of anti-inflammatory cytokines, such as IL-10 that inhibits the release of proinflammatory cytokines such as IL-6, IL-8 and TNF, limiting colitis development." (PMID 39966897, 2025). "Similarly, Ginkgetin suppresses IEC apoptosis through the EGFR/PI3K/AKT pathway, thereby improving experimental colitis." (PMID 39902073, 2024). "It has been reported that this p40 transactivates the EGFR pathway in in vitro models with the human colonic cell lines HT-29, T84, and LS174T and with mouse intestinal epithelial cells, as well as in vivo murine models of colitis induced by DSS." (PMID 38138057, 2023). "Aumolertinib, a novel third-generation EGFR-TKI, might be an effective alternative for the treatment of patients with NSCLC experiencing colitis from osimertinib." (PMID 35479327, 2022). "EGFR activation during the injury phase did not reduce the overall number of tumors, likely because mutational effects of AOM, and not differential colitis severity, in this model are the primary drivers of tumor initiation." (PMID 29904166, 2018). "An attractive hypothesis is that EGFR signaling restricts epithelial CXCL2 expression, thereby limiting recruitment of neutrophils, key components of the immune infiltrate in colitis, after DSS-induced epithelial damage." (PMID 29904166, 2018). "The active ingredients may act on 352 core protein targets, including EGFR, AKT1, PIK3R1, PIK3CB, and MAPK1, thereby modulating relevant pathways, such as MAPK and PI3K-Akt signaling pathways, and thus alleviating inflammation and intestinal damage in colitis." (PMID 40365509, 2025). "Although the essential roles of the epidermal growth factor receptor (EGFR), Wnt/β-catenin, Notch, and Hippo pathways for epithelium regeneration have been well investigated, data on the differentiation of GCs in IBD, which affects the mucus recovery in colitis, remain limited." (PMID 38997284, 2024). "In our porcine model of colitis, EGFR expression in the colon mucosa was not affected." (PMID 24001404, 2013). "Hence, we here investigated the therapeutic efficacy of an optimized nutritional intervention designed to inhibit increased aerobic glycolysis of tumor cells in the presence or absence of an EGFR-directed antibody-based therapy in a mouse model of colitis-driven CRC." (PMID 34830971, 2021). "Experimental colitis colonic and peritoneal macrophages and human CD14+ monocytes have been reported to express EGFR, but we did not detect EGFR expression in Ana-1 and THP-1 cells here." (PMID 27683110, 2016).
skin cancer (71 papers, 2009 to 2026). "Since EGFR-TK is a key regulator of cell proliferation, its aberrant activation is often linked to the development of various cancers, including skin cancer." (PMID 39587466, 2024). "The progression and metastasis of skin cancers is often associated with the overexpression of receptors for growth factors, such as the epidermal growth factor receptor EGFR on the surface of tumor cells." (PMID 38396841, 2024). "In summary, these data indicate that during tumorigenesis LRIG2 increases skin tumor progression, associated with activation of EGFR/ERBB4‐MAPK signaling." (PMID 31580518, 2019). "Ultraviolet radiation is one of the most important factors predisposing to skin cancer and is also known to activate EGFR." (PMID 19551138, 2009). "CCHCR1 is up-regulated in skin cancer and associated with EGFR expression." (PMID 31332212, 2019). "Among the tested formulations (RS-, SR-EGF-GNPs conjugates), the second one showed enhanced biological activities and growth inhibition in EGFR-overexpressing skin cancer cell line A431." (PMID 39940134, 2025). "By using a nanobody recognizing EGFR (αEGFR), we prepared the αEGFR-γδ T cells, which exhibited enhanced cytotoxicity toward A431 cells, an EGFR-positive human skin cancer cell line." (PMID 40842867, 2025). "Due to the varying levels of EGFR expression in the two cell lines (A431 and A549), the AuNPs-NmAb showed greater cytotoxicity in skin cancer cell lines (A431) than in lung cancer cell lines (A549)." (PMID 37803407, 2023). "In the experimental study, we cultured the A431 skin-cancer cell line in a serum-free medium and stimulated it with EGFR." (PMID 36832692, 2023). "Other suggested mechanisms include inhibiting the activation of the downstream adapter protein and also the epidermal growth factor receptor in human skin cancer cells (A431)." (PMID 37803407, 2023). "In skin cancer, IL-17 activates epidermal growth factor receptor (EGFR) and STAT 3 increasing the tumor growth." (PMID 38139369, 2023). "Since signaling through EGF and its receptor EGFR promotes skin cancer, EGF was used to promote the transformation of mouse epidermal cells JB6 P+ (the tumor promoter sensitive subline)." (PMID 35312729, 2022). "Among the tested EGF mutants (RS, SR), the GNP conjugate of the SR mutant showed enhanced biological activities and growth inhibition in EGFR-over expressing skin cancer cell line A431." (PMID 34512175, 2021). "Microvesicles released by lung, colorectal and skin cancer cells have been shown to transfer oncogenic EGFR to endothelial cells and to elicit EGFR-dependent MAPK and AKT activation in these cells." (PMID 32751440, 2020). "Lung, colorectal and skin cancer cells release EGFR-enriched EVs that can transfer oncogenic EGFR to ECs to activate EGFR-dependent MAPK and AKT, triggering ECs to express VEGF." (PMID 33363174, 2020). "While we have previously made advancements with 3D-SPT techniques and reported a wealth of information about EGFR trafficking in skin cancer A431 cells, 3D-SPT is currently limited by its low throughput (tracking one receptor complex at a time)." (PMID 31805710, 2019). "This study aimed to investigate theranostic strategies in colorectal and skin cancer based on fragments of cetuximab, an anti-EGFR mAb, labeled with radionuclide with imaging and therapeutic properties, 111In and 177Lu, respectively." (PMID 29777377, 2018). "EGF was used to promote transformation, because EGF and its receptor (EGFR) have been found as an important signaling pathway leading to cancer, including skin cancer." (PMID 28335476, 2017). "IKKα has been shown to be integrated into the EGFR/Ras/Erk pathway during mitosis and differentiation as well as in skin cancer development." (PMID 27121058, 2016). "The epidermal growth factor (EGF) receptor (EGFR) is an important mediator of skin cancer and belongs to the ErbB family of receptor tyrosine kinases (RTK)." (PMID 26910280, 2016).
skin cancer (continued). "The activation of epidermal growth factor receptor (EGFR) in skin cancers is closely related to the carcinogenic events including cell proliferation, migration and invasion." (PMID 25672851, 2015). "E5 is involved in the transformation of fibroblasts and keratinocytes as well as tumour progression of skin cancer in transgenic mice via epidermal growth factor receptor (EGFR) activation." (PMID 25699089, 2014). "Taken together, these results demonstrate that EGFR signaling is important for keratinocyte proliferation, survival and skin tumor promotion." (PMID 21297902, 2010). "Grafts of EGFR-null keratinocytes transformed with v-H-ras yield skin tumors that are much smaller than wild-type keratinocytes, which demonstrates that EGFR signaling contributes to tumor growth." (PMID 21297902, 2010). "To study the role of CCHCR1 in KC proliferation and transformation, we investigated CCHCR1 protein expression by immunohistochemistry in different skin tumors in relation to EGFR, its downstream target cyclin-D1, and the hyperproliferation marker Ki67." (PMID 19551138, 2009). "In addition to As-T cells, we also observed that overexpression of miR-218-5p inhibited EGFR expression in chromium (Cr)-induced transformed cells (Cr-T) and skin cancer cell line A431, indicating that EGFR is a direct target of miR-218-5p." (PMID 36831545, 2023). "Several signaling pathways are involved in the mechanism of polyphenols against skin cancer metastasis, including NF-κB, epidermal growth factor receptor/mitogen activated protein kinase (EGFR/MAPK), and phosphatidylinositide 3- kinases/protein kinase B (PI3K/Akt)." (PMID 36431932, 2022). "In this review, we introduce nicotinamide adenine dinucleotide phosphate (NADPH) oxidase and epidermal growth factor receptor (EGFR) as molecular targets that can complement antioxidant activity and effectively inhibit skin cancer via the regulation of various signaling networks." (PMID 34943012, 2021). "In addition, we demonstrate that the reduced proliferative capacity of HPV + cells observed upon JNK1/2 inhibition is at least partially due to a defect in EGFR signalling, which has previously been shown in skin tumours in which the JUN gene has been deleted." (PMID 33303976, 2021). "EGFR expression was detected in 25% of the oral and 53% of the skin tumors." (PMID 31996230, 2020). "Additionally, skin cancer-derived exosomes can promote angiogenesis by delivering Epidermal Growth Factor receptor (EGFR) and miR-9 to ECs." (PMID 29515996, 2018). "What is more, EGFR is also common in types of different cancers including skin cancer." (PMID 34466445, 2018). "As EGFR activation in association with increased COX-2 expression is involved in photocarcinogenesis of keratinocytes and EGFR seems to be a key mediator of UVB-induced skin cancer, PE4 might also be effective in skin cancer prevention." (PMID 27322232, 2016). "Thus, our finding here that Dsg2 can modulate EGFR activation is a critical link that connects cell-cell adhesion to mitogenic signaling in skin cancer development." (PMID 26918609, 2016). "The role of EGFR/ErbB signaling in mouse skin tumor promotion has been extensively studied." (PMID 21297902, 2010). "Moreover, a previous work on skin cancer cells using the same Mel-AF peptide as this work also suggested that this peptide could diminish EGFR activity by suppressing its expression." (PMID 40141140, 2025). "Epidermal growth factor receptor tyrosine kinase (EGFR-TK, PDB ID: 1M17) was selected for prodigiosin’s anticancer potential against skin cancer, aiming to disrupt uncontrolled cell growth." (PMID 39587466, 2024). "The autonomous EGFR and ERBB4 receptors are important for tissue development and homeostasis, but they also play a major role in tumorigenesis, particularly in skin cancer." (PMID 31580518, 2019).
skin cancer (continued). "Gilaberte and colleagues studied recurrences and aggressiveness of skin tumors non respondent to PDT, reporting an increased Epidermal Growth Factor Receptor (EGFR) expression after MAL-PDT." (PMID 29382133, 2018). "Here, we addressed the effects of HPV8E6 on the UV-activated EGFR signaling and the implications for HPV8E6 mediated skin tumor formation in transgenic mice." (PMID 29176966, 2017). "In the past, molecular pathways critically involved in the development of BCC and SCC, including EGFR/ERK and IGFR signalings, have been identified, leading to new pharmacological approaches for the treatment of these skin tumors." (PMID 28445952, 2017). "To investigate the molecular mechanism behind the accelerated skin tumor growth in the N-WASPKOG12D mice, we isolated protein lysates (37 days post TAM) from the skin of both groups of mice and carried out Western blot analyses for EGFR, P-Erk, and Glut1." (PMID 37760426, 2023). "Therefore, in addition to directly scavenging ROS using antioxidants, modulating EGFR, PI3K, Src, and MAPK activity, such as by phosphorylation, would be a remarkable strategy to prevent UV-induced skin damage and skin cancer." (PMID 34943012, 2021). "Various materials have been discussed regarding the prevention of skin cancer via the regulation of NOX and EGFR following activation with UV and subordinate factors; however, research on the direct interplay between the materials and these molecules is incomplete." (PMID 34943012, 2021). "By summarizing the results of our research and that of other scientists, we aim to introduce materials that could prevent or control skin cancer and skin diseases through the regulation of NOX and EGFR." (PMID 34943012, 2021). "Transgenic AREG overexpression in keratinocytes leads to inflammatory epidermal hyperplasia without spontaneous development of skin tumors, suggesting that aberrant EGFR signaling is not sufficient to drive tumorigenesis." (PMID 33497366, 2021). "It is striking that the features that distinguish skin tumors developed by C-IKKα/TgAC mice, i.e., MMP-9 and VEGF-A upregulation and increased EGFR activation are the same that characterize the skin tumors arisen in mice lacking IKKα or expressing diminished levels of this protein." (PMID 27121058, 2016). "Furthermore, since some authors have reported that COX-2-derived PGE2 synthesis is a key event of skin tumor promotion in response to UV, COX-2 suppression resulting from EGFR inhibition is worthy of further investigation." (PMID 23878744, 2013). "Additionally in A431NS skin cancer cells, Sym004 did not promote phosphorylation of EGFR Y1045, which is the major binding site for Cbl ubiquitin ligases shown to be critical for EGFR ubiquitylation." (PMID 31959764, 2020). "Furthermore, induction of EGFR appears to be responsible for the skin tumor development in IKKαF/F/K15.Cre mice lacking IKKα in keratinocytes." (PMID 27121058, 2016). "For instance, a study on Pongamia pinnata extract against skin cancer demonstrated that MD simulations were essential in verifying the stability of the complexes EGF-Pazopanib, EGFR-Pongachromene, and ERBB2-Vitexin up to 100 ns without any major fluctuation." (PMID 40627263, 2025). "However, inhibitors to Epidermal growth factor receptor (EGFR) and MAP kinse-ERK kinase (MEK) (a downstream molecule in the EGFR pathway) did not change the elevated level of EREG in TSC skin tumor." (PMID 24748662, 2014).